DDX41 (DEAD-box helicase 41)
Diseases named in the same sentence as DDX41 in open-access papers (continued):
Sharing a sentence is not in itself a finding about the gene and the disease.
DDX41 also shares sentences with these, for which no sentence is quoted: chronic lymphocytic leukemia (2 papers); Li-Fraumeni syndrome (2); liver cancer (2); Thrombocytopenia (2); acute erythroleukemia (1); acute leukemia (1); Adult onset (1); aplastic anemia (1); B-cell lymphoma (1); Bloom syndrome (1); bone marrow failure (1); chronic myeloid leukemia (1); clear cell renal cell carcinoma (1); colorectal cancer (1); coronary artery disease (1); fatty liver disease (1); follicular lymphoma (1); hereditary tumor syndromes (1); Hodgkins lymphoma (1); influenza (1); lung fibrosis (1); lymphoma (1); malignant peripheral nerve sheath tumor (1); measles (1); mesothelioma (1); metabolic disorders (1); Mono (1); neurodegenerative disease (1); neutropenia (1); Obesity (1).
A further 3 diseases each share a sentence with DDX41 in 1 paper.